CASD1 (CAS1 domain sialic acid O acetyltransferase 1)
Description:
Key enzyme in the biosynthesis of O-acetylated (O-Ac) sialoglycans such as gangliosides O-AcGD3 and O-AcGD2, which affect various processes such as cell-cell interactions, host-pathogen recognition. Catalyzes the transfer of an acetyl group from a donor, the acetyl-coenzyme-A molecule (acetyl-CoA), to the C7/8/9 OH-position of a sialic acid residue. The primary site of O-acetyl group transfer on sialic acid seems to depend on cell type and can be C7, from which the O-acetyl group could subsequently migrate to the C8 and then to the C9 position, or at C9 with possibility of migrating to the C8 and then to the C7 position. Together with ST8SIA1 (GD3 synthase) it increases the levels of ganglioside Ac-O-7-GD3. Can transfer the acetyl group from acetyl-CoA to free sialate (N-acetylneuraminate, Neu5Ac) in vitro, but has preferred substrate specificity for CMP-activated sialate (CMP-Neu5Ac), resulting in the formation of 9-O-acetylated CMP-Neu5Ac (CMP-Neu5,9Ac2). CMP-Neu5,9Ac2 may be used by sialyltransferases as a sialate donor for glycoconjugate acceptors such as ganglioside GD3. O-acetylation at position C9 of ganglioside GD3 can counteract the pro-apoptotic effects of the ganglioside GD3 in tumor cells.
Synonyms: Cas1p; SOAT; C7orf12; Nbla04196; FLJ21213; FLJ21879; Cas1
Tractability: Antibody: UniProt predicts a signal peptide or a membrane-spanning region. PROTAC: its protein half-life has been measured.
Gene: Protein-coding gene on chromosome 7 (94,509,219 to 94,557,302, forward strand). Ensembl gene ENSG00000127995.
Subcellular location: Golgi apparatus membrane
Subcellular location (Human Protein Atlas): Nucleoplasm
Gene Ontology:
Molecular function: N-acetylneuraminate 9-O-acetyltransferase activity
Biological process: carbohydrate metabolic process
Cellular component: Golgi membrane; Golgi apparatus
Genetic constraint (gnomAD): Loss-of-function variants: 16 observed, 39.37 expected, observed/expected ratio (o/e) 0.41, 90% interval 0.27 to 0.62. The upper end of that interval is the gene's LOEUF score, 0.62, which puts it in group 2 of 6, group 1 being the genes least tolerant of losing a copy. Missense variants: 487 observed, 559.69 expected, observed/expected ratio (o/e) 0.87, 90% interval 0.81 to 0.94. Synonymous variants: 207 observed, 195.5 expected, observed/expected ratio (o/e) 1.06, 90% interval 0.94 to 1.19.
Homologues: Orthologues: chimpanzee CASD1 (99% identical), macaque CASD1 (99% identical), dog CASD1 (98% identical), pig CASD1 (97% identical), mouse Casd1 (95% identical), rat Casd1 (94% identical), guinea pig CASD1 (93% identical), rabbit CASD1 (91% identical), tropical clawed frog casd1 (75% identical), zebrafish casd1 (67% identical), Drosophila melanogaster CG2938 (35% identical).
Diseases named in the same sentence as CASD1 in open-access papers:
CASD1 is named in the same sentence as 16 diseases in open-access papers, as found by Europe PMC text mining. Sharing a sentence is not in itself a finding about the gene and the disease. The quoted sentences say what the papers report.
breast carcinoma (2 papers, 2021 to 2022). "Overexpression using plasmid transfection and siRNA strategies was used to modulate CASD1 expression in SUM159PT breast cancer cell line." (PMID 34208013, 2021). "The aim of this study was to determine the involvement of CASD1 in GD2 O-acetylation in breast cancer." (PMID 34208013, 2021). "However, high CASD1/OAcGD2 expression increases the migration and invasion of SUM159PT triple negative breast cancer cells, and OAcGD2 is a marker of breast cancer stem cells, which have the highest tumor-initiating capacity." (PMID 35267607, 2022).
colon cancer (2 papers, 2023). "In comparison to the wild type and SIAE knockout cells, our results showed significantly low levels of 25kDa cleaved/inactive PARP1 fragments in the CASD1 knockout lung and colon cancer cells when challenged with mitoxantrone." (PMID 37377914, 2023). "We employed lung cancer (A549) and colon cancer (HCT 116) cells whose sialate O-acetyl transferase (CASD1) gene and sialate O-acetyl esterase (SIAE) gene have been removed via CRISPR Cas 9 gene editing." (PMID 37377914, 2023). "Our results revealed consistently significant high levels of the pro-survival protein BcL-2 in CASD1 knockout cells compared to the wild type and SIAE knockout cell lines for the lung cancers and wild type for the colon cancers." (PMID 37377914, 2023). "As such, we investigated BCRP expression and function as well as survival in control, CASD1 knockout cells that lack acetylated Sia, and SIAE knockout cells that over-express acetylated Sia in lung and colon cancer cell line." (PMID 37377914, 2023). "More specifically, when Sia acetyl modifying protein, CASD1, is knocked out via CRISPR Cas9 genome editing, lung and colon cancer cells tend to upregulate their activated EGFR expression levels to compensate for the genetic aberration." (PMID 37687086, 2023). "Specifically, we investigated how CASD1 gene knockout (i.e., lack of acetyl Sia) affects the activity of three novel Cucurbitacin-inspired estrone analogs (CIEAs), MMA 320, MMA 321, and MMA 294, in in vitro models of lung and colon cancer cells." (PMID 37687086, 2023).
Autoimmunity (1 paper, 2021). The occurrence of an immune reaction against the organism's own cells or tissues. "The role of sialic acid O-acetylation including SIAE, CASD1, and interactions with Siglecs in autoimmunity and inflammation is therefore open for investigation." (PMID 34157283, 2021). "Inhibitors of CASD1 might be useful to target sialic acid O-acetylation in cancer to facilitate GD3-mediated apoptosis, to trigger immune inhibitory Siglec signaling in autoimmunity, or to increase the immunogenicity of capsular sialic acids in bacteria." (PMID 34157283, 2021).
glioblastoma (1 paper, 2021). The most malignant astrocytic tumor (WHO grade IV). "Further studies are required to determine whether CASD1 has a more general role in OAcGD2 biosynthesis in cancers with high OAcGD2 levels, such as neuroblastoma and glioblastoma." (PMID 34208013, 2021).
lung adenocarcinoma (1 paper, 2023). A carcinoma that arises from the lung and is characterized by the presence of malignant glandular epithelial cells. "Consistent with our experimental findings that CASD1 knockout confers resistance to mitoxantrone and promotes cell survival, we also found that CASD1 expression favors survival in clinical lung Adenocarcinoma (LUAD) samples." (PMID 37377914, 2023). "RNASeq data analysis of clinical samples revealed higher CASD1 expression as a favorable marker of survival in lung adenocarcinoma." (PMID 37377914, 2023).
lung carcinoma (1 paper, 2023). "Conversely, the CASD1 knockout cells were observed to be more refractory (2- and 3-fold resistance for colon and lung cancer cells respectively) to mitoxantrone." (PMID 37377914, 2023). "Our results showed significantly high growth rate in CASD1 knockout lung cancer cells compared to wildtype and SIAE knockout cell lines." (PMID 37377914, 2023).
melanoma (1 paper, 2020). A malignant, usually aggressive tumor composed of atypical, neoplastic melanocytes. "CASD1 (CAS1 Domain-Containing Protein 1) is ubiquitously expressed and up-regulated in human primary cell lines, melanoma and liver-derived cells." (PMID 32192217, 2020).
virus infection (1 paper, 2019). "To look more closely at the expression and roles of 7,9-O- and 9-O-Ac modifications and their effects on viral infections, we prepared glycoengineered cell lines that lacked these modifications or that expressed higher levels of CasD1." (PMID 31796537, 2019).
cancer (8 papers, 2015 to 2025). A tumor composed of atypical neoplastic, often pleomorphic cells that invade other tissues. "Our MTT assay data revealed the aggressive and proliferative characteristics associated with CASD1 knockout cancer cells compared to SIAE knockouts, aligning with findings from a separate study." (PMID 39717751, 2024). "Knocking out SIAE gene generated cancer cells with O-acetylated sialic acid, while knocking out CASD1 gene resulted in cancer cells with de-O- acetylated sialic acid." (PMID 39717751, 2024). "The cancer cell lines featuring CASD1 knockouts, indicative of deacetylated sialic acid, exhibited increased binding with all three Selectins." (PMID 39717751, 2024). "The results further showed a reduced sensitivity/response in CASD1 knockout cell lines of both cancer cells as compared to the Wild types and SIAE knockout cells." (PMID 37377914, 2023). "Re-expression of 9-O-Ac-GD3 in cancer is presumably the result of altered expression of CASD1, SIAE, and glycosyltransferases (e.g., ST3GAL5, ST8SIA1), which was observed in human medulloblastoma samples and ALL." (PMID 34157283, 2021). "This opens new experimental avenues for the development of effective therapeutic strategies targeting CASD1 to regulate pathological changes in the 9-O-acetylation status and to combat drug-resistant cancer cells in ALL, whose survival crucially depend on 9-O-acetylation." (PMID 26169044, 2015). "However, no significant increase was recorded in BCRP level for BMA-treated CASD1 knockout cancer cells suggesting that lysosomal degradation pathway may also be responsible for modulating levels of acetyl modified glycoproteins including BCRP." (PMID 37377914, 2023). "Consequently, targeting OAcGD2 and CASD1 in cancers using immunotherapy, but also transcriptional or functional inhibitors of CASD1, might be another strategy used to decrease the malignant properties of cancer cells." (PMID 35267607, 2022). "The CASD1 knockout (ΔCASD1) cells represented cancer cells with deacetylated sialic acid, while the SIAE knockout (ΔSIAE) cells represented cancer cells with acetylated sialic acid." (PMID 39717751, 2024). "Importantly, CASD1 overexpression could modulate the expression of other O-acetylated gangliosides or sialylated glycosphingolipids (Globo-, Lacto-/Neolacto-series), which could also modify the biological properties of cancer cells." (PMID 34208013, 2021). "The human sialate O-acetyltransferase CASD1 is an important Golgi protein that is essential for O-acetylation of sialic acids during the maturation of glycans and a potential target for preventing cancer progression." (PMID 40752577, 2025). "Clearly, more studies are needed to understand the effects of CASD1 and SIAE activity in cancer." (PMID 34157283, 2021). "However, the transwell migration assay revealed that the migration of cells containing de-O-acetylated-Sia (CASD1 knockout cell lines) in CASD1 mutant cells in A549 cancer cells exceeded that of the control cell line but not in HCT116." (PMID 39717751, 2024).
infection (1 paper, 2019). The state of being infected such as from the introduction of a foreign agent such as serum, vaccine, antigenic substance or organism. "Although the CasD1-OX cells had detectable surface levels of 9-O-Ac, these levels were lower than in WT MDCK cells and could be below the receptor levels required for efficient infection by these viruses." (PMID 31796537, 2019).
CASD1 also shares sentences with these, for which no sentence is quoted: tumor (4 papers); carditis (1); colon adenocarcinoma (1); colorectal cancer (1); neuroblastoma (1); triple-negative breast carcinoma (1).